C1orf53 (chromosome 1 open reading frame 53)
Tractability: No criterion of Open Targets' tractability assessment is met for any kind of drug.
Gene: Protein-coding gene on chromosome 1 (197,902,449 to 197,907,368, forward strand). Ensembl gene ENSG00000203724.
Subcellular location (Human Protein Atlas): Vesicles; Aggresome
Gene Ontology:
Cellular component: mitochondrion
Genetic constraint (gnomAD): Loss-of-function variants: 17 observed, 8.2 expected, observed/expected ratio (o/e) 2.07. That is too few expected variants to judge how well the gene tolerates losing a copy. Missense variants: 207 observed, 120.29 expected, observed/expected ratio (o/e) 1.72, 90% interval 1.53 to 1.91. Synonymous variants: 91 observed, 52.64 expected, observed/expected ratio (o/e) 1.73, 90% interval 1.45 to 1.95.
Homologues: Orthologues: chimpanzee C1H1orf53 (100% identical), macaque C1H1orf53 (91% identical), pig C1orf53 (69% identical), rat C13h1orf53 (67% identical), mouse 2310009B15Rik (66% identical), dog C1orf53 (63% identical), tropical clawed frog c4h1orf53 (43% identical), zebrafish C22H1orf53 (34% identical), Caenorhabditis elegans F45E12.5 (30% identical). Paralogues in human: MRPL14 (12% identical).
Diseases named in the same sentence as C1orf53 in open-access papers:
C1orf53 is named in the same sentence as 1 disease in open-access papers, as found by Europe PMC text mining. Sharing a sentence is not in itself a finding about the gene and the disease. The quoted sentences say what the papers report.
tumor (1 paper, 2023). "ATF5 was significantly expressed on Mono/Macro and pDC subgroups in tumor cells, whereas C1orf53 was predominantly expressed on Mono/Macro subgroup and SMARCD3 was predominantly expressed on Mast subgroup." (PMID 37859813, 2023).